DMD (dystrophin)
Diseases named in the same sentence as DMD in open-access papers (continued):
Sharing a sentence is not in itself a finding about the gene and the disease.
Becker muscular dystrophy (continued). "Pathogenic variants in the DMD gene can also cause Becker muscular dystrophy (BMD), which is a milder disease with a later onset and a slower progression than DMD." (PMID 40693222, 2025). "All Becker muscular dystrophy (BMD) mice showed truncated dystrophin expression and decreased sarcolemmal neuronal nitric oxide synthetase (nNOS) expression." (PMID 40094282, 2025). "In contrast, patients with Becker muscular dystrophy (BMD) produce partially functional dystrophin and present a milder phenotype than DMD." (PMID 40695994, 2025). "For example, a rare case was described in which a deletion encompassing approximately 46% of the coding sequence of the DMD gene led to a mild Becker muscular dystrophy phenotype." (PMID 41614822, 2025). "On the other hand, Becker muscular dystrophy (BMD) is marked at the cellular level by residual dystrophin activity and is clinically manifested by muscle cramps and weakness." (PMID 40451248, 2025). "Such cases have been reported for the DMD gene, where a 2-bp deletion in exon 74 of DMD was found in a patient with Becker muscular dystrophy." (PMID 41244983, 2025). "Preclinical studies conducted in MSTN-null mdx mice, a model of DMD and Becker muscular dystrophy (BMD) featuring a premature stop codon in the gene for dystrophin, have demonstrated increased muscle size and strength." (PMID 39340593, 2025). "A third 9U proband (IC_AIM_00788) had an in-frame deletion of exon 45–48 in Dystrophin, suggesting Becker Muscular Dystrophy (BMD), which in retrospect better fitted clinical features." (PMID 38664571, 2024). "Becker muscular dystrophy (BMD) is an X-linked recessive disorder characterized by mutations in the dystrophin gene located on chromosome Xp21.1, which codes for the central protein in the dystrophin-glycoprotein complex in skeletal and heart muscle cells." (PMID 39640169, 2024). "Molecular analysis of the dystrophin gene, undertaken in 2009, showed deletion of exons 5-6-7-8, confirming the diagnosis of Becker muscular dystrophy." (PMID 39640169, 2024). "A recent study detected increased CK in 57% of women with pathogenic dystrophin gene variants, including DMD carriers and Becker muscular dystrophy mutation carriers." (PMID 39075955, 2024). "By contrast, mutations that maintain the reading frame and allow the production of a shorter, but partially functional, dystrophin lead to Becker muscular dystrophy (BMD), a milder form of dystrophinopathy." (PMID 38607013, 2024). "An out-of-frame DMD deletion is intended to be changed into an in-frame deletion that resembles BMD (Becker Muscular Dystrophy) using CRISPR DNA editing techniques." (PMID 39051216, 2024). "DMD in-frame mutations produce truncated DYSTROPHIN proteins that are associated with less severe clinical manifestations, known as Becker muscular dystrophy (BMD)." (PMID 38891104, 2024). "In Becker muscular dystrophy (BMD), the truncated version of dystrophin is being produced, which causes milder symptoms and achieves a longer lifespan in Becker individuals than those with DMD." (PMID 39595938, 2024). "A milder allelic Becker muscular dystrophy (BMD; MIM number: 300376) is caused by mutations that produce dystrophin with abnormal size." (PMID 39588385, 2024). "No studies were listed in this table in which the population also included carriers of Becker muscular dystrophy, and the data were presented together with that of female DMD carriers." (PMID 39075955, 2024). "Mutations in the DMD gene can either result in the formation of an incomplete, unstable form of DYSTROPHIN, to a complete absence or to the expression of very low levels of DYSTROPHIN as seen in BMD (Becker Muscular Dystrophy)." (PMID 38585275, 2024). "Schizophrenia and attention deficit co-occur in individuals with neuromuscular diseases like Becker muscular dystrophy, featuring “in-frame” DMD gene deletions." (PMID 39202552, 2024).
Becker muscular dystrophy (continued). "The muscle biopsy result raised suspicion of Becker muscular dystrophy, leading to the analysis of F2’s Dystrophin gene through a multiplex ligation-dependent probe amplification method." (PMID 38812636, 2024). "For example, the bmx mouse model of Becker muscular dystrophy would provide a backdrop of partially functional Becker-like dystrophin isoforms as opposed to dystrophin-null mdx52 mice." (PMID 38770680, 2024). "Becker muscular dystrophy (BMD) is a genetic neuromuscular disease of growing importance caused by in‐frame, partial loss‐of‐function mutations in the dystrophin (DMD) gene." (PMID 36628607, 2023). "A 28‐year old mother of two boys who carry a diagnosis of Becker muscular dystrophy underwent routine maternal carrier testing via deletion/duplication analysis of the DMD gene by aCGH." (PMID 36424846, 2023). "Becker muscular dystrophy (BMD) is a milder version of the disease and arises from dystrophin mutations that lower dystrophin expression or lead to the accumulation of an internally truncated dystrophin protein that reduce functional capacity." (PMID 37627841, 2023). "Deletions or duplications in the DMD gene were detected in four male infants consistent with DMD or Becker muscular dystrophy." (PMID 37350320, 2023). "By excluding exon 45 during mRNA processing and restoring the frame, a dystrophin isoform protein is produced that is similar to the protein found in Becker's muscular dystrophy." (PMID 38283433, 2023). "For instance, the identification of dystrophin point mutations or internal deletions in patients with DMD or Becker Muscular Dystrophy (BMD), a milder form of the disease, has provided insights into the relevance of the different dystrophin protein domains." (PMID 37384252, 2023). "This case describes a female patient with biallelic DMD deletions who has three sons with Becker muscular dystrophy due to two different DMD deletions." (PMID 36424846, 2023). "On the other hand, Becker Muscular Dystrophy (BMD) is a less severe form of dystrophin-related disease." (PMID 35866748, 2022). "The notion of miniaturized dystrophin was based on a Becker muscular dystrophy patient, who remained ambulatory for seven decades despite a deletion of nearly half of the DMD gene." (PMID 36360257, 2022). "Becker muscular dystrophy and DMD are a subgroup of X-linked recessive neuromuscular disorders called dystrophinopathies that arise from mutations in the dystrophin gene." (PMID 35549971, 2022). "Mutations involving a part of the central rod domain of the dystrophin protein can still produce a partially functional protein that leads to a milder condition of the DMD, Becker muscular dystrophy (BMD)." (PMID 35052837, 2022). "Becker muscular dystrophy (BMD), which is also caused by mutations in the DMD gene, results in a variable but milder phenotype." (PMID 36514350, 2022). "Duchenne's muscular dystrophy (DMD) and Becker's muscular dystrophy (BMD), the two forms of X-linked muscular dystrophy are caused by mutations in the Dystrophin gene." (PMID 34983696, 2022). "Exon skipping of patients’ DMD pre-mRNA induced by antisense oligonucleotides (AOs) is expected to produce shorter but partly functional dystrophin proteins, such as those possessed by patients with the less severe Becker muscular dystrophy." (PMID 34698059, 2021). "A milder variant of DMD is Becker Muscular Dystrophy (BMD), caused by deletions in the dystrophin gene that maintain the open reading frame, resulting in the production of a shorter but partially functional dystrophin protein." (PMID 34832896, 2021). "Pathogenic variants, such as deletions, duplications, and small mutations, in the DMD gene encoding dystrophin account for both DMD and Becker muscular dystrophy (BMD), a milder form of the disease with later onset and slower progression." (PMID 34421809, 2021).
Becker muscular dystrophy (continued). "Additionally, DMD exons 45–55 deletion is known to be associated with a remarkably mild phenotype, called Becker muscular dystrophy (BMD)." (PMID 34831073, 2021). "In contrast to DMD, Becker muscular dystrophy (BMD) is caused by in-frame mutations in dystrophin encoding gene- DMD - resulting in the expression of functional truncated dystrophin; therefore, BMD patients show the moderate form of disease with late-onset muscular dystrophy." (PMID 34804433, 2021). "Out of frame mutations usually result in the complete ablation of dystrophin protein expression (DMD) while in frame mutations usually result in partial dystrophin expression and Becker muscular dystrophy (BMD), a milder form of dystrophinopathy." (PMID 33663533, 2021). "The adoption of a truncated version of dystrophin as a possible treatment for DMD is based on a Becker muscular dystrophy patient who remained ambulatory for seven decades despite a deletion of nearly half his DMD gene." (PMID 33309881, 2021). "Editor's choice: The newly established rat model carrying in-frame mutations in the Dmd gene exhibits the dystrophic phenotype and abnormal dystrophin expression profile, similar to patients with Becker muscular dystrophy." (PMID 32859695, 2020). "Becker muscular dystrophy, a variable but milder form of muscular dystrophy, also arises from dystrophin gene lesions but these are generally in-frame deletions in the central rod domain." (PMID 33019779, 2020). "This reading frame rule largely explains the genotype/phenotype correlations observed and has been exploited through exon skipping to convert DMD into a milder Becker muscular dystrophy (BMD)." (PMID 32597486, 2020). "These approaches include converting the DMD mutation into an in-frame deletion mutation found in the milder Becker muscular dystrophy (BMD), and the gene transfer of a compact dystrophin called microdystrophin." (PMID 32988972, 2020). "After this finding, the patient was re-examined showing a phenotype compatible with a Becker muscular dystrophy that was confirmed by a reduction of dystrophin in the muscle biopsy immunostaining." (PMID 32403337, 2020). "The existence of ‘hot-spots’ for DMD gene mutations, and exceptions to the reading frame hypothesis, has instigated many DMD and Becker muscular dystrophy (BMD) genotype-phenotype relationship studies." (PMID 31836945, 2020). "A milder allelic disorder, Becker muscular dystrophy (BMD), also arises from mutations in the DMD gene, most commonly in-frame deletions that allow synthesis of an internally truncated protein that retains some function." (PMID 32630425, 2020). "In DMD, internally deleted forms of dystrophin are known to be functional and result in a milder form of disease known as Becker muscular dystrophy (BMD)." (PMID 31582396, 2019). "The exon skipping approach aims to restore the disrupted dystrophin reading frame, to allow the production of partially functional dystrophins, such as found in the less severe Becker muscular dystrophy." (PMID 30672725, 2019). "Duchenne (DMD, OMIM #301200) and Becker muscular dystrophies (BMD, OMIM #300376) are X-linked recessive degenerative disorders caused by mutations in the dystrophin gene (DMD, HGNC:2928)." (PMID 31817415, 2019). "This shorter dystrophin, with lower molecular weight, leads to a milder form of dystrophinopathy, called Becker muscular dystrophy (BMD)." (PMID 30794581, 2019). "The clinically milder Becker Muscular Dystrophy (BMD, OMIM 300376) is also caused by mutations in the DMD gene." (PMID 29474464, 2018). "A milder form of disease, Becker muscular dystrophy (BMD), is generally caused by in-frame deletions in the dystrophin gene that lead to an internally truncated dystrophin protein that retains partial function." (PMID 29411170, 2018).
Becker muscular dystrophy (continued). "The reading frame can be restored by antisense oligonucleotide (AON)-mediated exon skipping, allowing production of internally deleted, but partially functional dystrophin proteins as found in the less severe Becker muscular dystrophy." (PMID 29466448, 2018). "In a separate report, we showed that miR-146a participates in a muscular dystrophy feedback loop wherein it specifically inhibits the production of dystrophin in Becker muscular dystrophy and in a mouse model of DMD exon skipping." (PMID 29883261, 2018). "Exon skipping aims to convert out-of-frame mRNA to in-frame mRNA and induce the production of internally-deleted dystrophin as seen in the less severe Becker muscular dystrophy." (PMID 30544634, 2018). "Accordingly, internally deleted but partially functional Dystrophin protein is created from the modified mRNA, similar to what is observed in the milder dystrophinopathy Becker muscular dystrophy." (PMID 29847600, 2018). "In all these strategies, different dystrophin proteins, often internally deleted, are produced, similar to those found in patients with the milder DMD allelic variant, Becker muscular dystrophy (BMD)." (PMID 29579078, 2018). "The most common forms, DMD and Becker muscular dystrophy (BMD), are a result of mutations of the DMD gene on the X chromosome that code for the large sarcolemmal protein dystrophin." (PMID 28596791, 2017). "Becker muscular dystrophy (BMD) is a milder form, also caused by mutations in dystrophin gene." (PMID 28738778, 2017). "Becker muscular dystrophy (BMD), a genetic disorder of X-linked recessive inheritance, is caused by mutations of Dystrophin gene located at Xp21.2." (PMID 27955624, 2016). "His CK was elevated (19,000 U/Dl), genetic testing showed a deletion of DMD exon 5 and he was diagnosed with Becker’s muscular dystrophy at the age of 8-years." (PMID 26745801, 2016). "Restoration of the reading frame would allow the production of a shorter but partly functional dystrophin protein as seen in Becker muscular dystrophy patients." (PMID 26623937, 2015). "In-frame deletions often generate truncated dystrophin and result in the milder Becker muscular dystrophy (BMD)." (PMID 25740330, 2015). "We report a dystrophinopathy patient with an in-frame deletion of DMD exons 45–47, and therefore a genetic diagnosis of Becker muscular dystrophy, who presented with a more severe than expected phenotype." (PMID 26247048, 2015). "Mutations that conserve the open reading frame produce reduced quantities of dystrophin or a dysfunctional or truncated form of dystrophy, resulting in Becker muscular dystrophy (BMD), a less severe phenotype." (PMID 26089900, 2015). "A recent study by our group showed that muscle inflammation is linked to the production of TNF-alpha-induced microRNAs that target the dystrophin mRNA and inhibit dystrophin translation in Becker muscular dystrophy patients." (PMID 26634117, 2015). "SSO-mediated exon skipping in dystrophin pre-mRNA can restore the reading frame and allow the expression of a truncated but functional dystrophin similar to that found in Becker muscular dystrophy patients, who have relatively milder symptoms." (PMID 24935206, 2014). "Becker muscular dystrophy (BMD) is a condition in which disruption in the dystrophin gene and the subsequent decrease in cytoplasmic dystrophin cause α- and βDG accumulation to be reduced at the sarcolemma." (PMID 24824861, 2014). "An allelic disorder, Becker muscular dystrophy (BMD), also arises from mutations in the DMD, and these are most commonly in-frame deletions that lead to synthesis of an internally deleted dystrophin isoform that retains some function." (PMID 24643206, 2014). "Becker muscular dystrophy (BMD) also results from mutations or deletions in the dystrophin gene, but BMD mutations allow for expression of partially functional dystrophin protein and are typically associated with phenotypically milder muscle disease than is seen in DMD." (PMID 24505439, 2014).
Becker muscular dystrophy (continued). "Alternately, in a porcine model of Becker muscular dystrophy, relative abundance of alpha-dystroglycan was decreased, consistent with a reduction in expression of the dystrophin-glycoprotein complex in affected muscle." (PMID 24824861, 2014). "At 18 months of age, Becker muscular dystrophy was diagnosed (deletion of exons 45–47 in the locus of dystrophin)." (PMID 23365767, 2013). "An allelic, less severe form of the disease, Becker muscular dystrophy (BMD) is caused by mutations that maintain the open reading frame and allow synthesis of internally deleted, partially functional dystrophin proteins." (PMID 22359642, 2012). "Among 65 Becker muscular dystrophy patients, we identified 12 patients who have rimmed vacuoles and 11 patients who have deletions in exons 45–48 in DMD gene." (PMID 23251671, 2012). "This improved description of the dystrophin central rod domain strongly supports the severity grading of Becker muscular dystrophy (BMD)." (PMID 21901138, 2011). "By contrast, patients with Becker muscular dystrophy (BMD) also have mutations in the DMD gene, but produce a partially functional dystrophin protein." (PMID 21824387, 2011). "This new integrative view is strongly supported by the previous experimental works that investigated the isolated domains and the observed heterogeneity of the severity of dystrophin related pathologies, especially Becker muscular dystrophy." (PMID 21901138, 2011). "This therapy uses AOs to modify splicing during pre-RNA processing, such that a DMD-associated exon is removed and a shorter but partially functional Becker muscular dystrophy (BMD)-like dystrophin isoform is produced." (PMID 22013876, 2011). "Becker muscular dystrophy (BMD) is a rare X-linked recessive neuromuscular disorder, frequently caused by in-frame deletions in the DMD gene that result in the production of a truncated, yet functional, dystrophin protein." (PMID 39099311, 2025). "Becker muscular dystrophy (BMD), an X-linked muscle disorder, is characterized by progressive muscle wasting and weakness, mostly caused by an in-frame variant in DMD encoding the sarcolemmal protein dystrophin." (PMID 40094282, 2025). "An SNP microarray revealed an interstitial duplication in exon 55 of DMD suggestive of Becker Muscular Dystrophy (BMD), but his degree of delays led to follow‐up exome sequencing revealing a pathogenic CSNK2A1 variant diagnostic for Okur–Chung Neurodevelopmental Syndrome." (PMID 39915227, 2025). "According to immunohistochemical analysis, the patient’s dystrophin levels were lower than in control samples but were sufficient to cause Becker muscular dystrophy rather than the more severe Duchenne phenotype." (PMID 41244983, 2025). "In contrast, mutations in the DMD gene that do not disrupt the reading frame are typically associated with a milder phenotype known as Becker muscular dystrophy (BMD)." (PMID 39596689, 2024). "However, in Becker muscular dystrophy (BMD) patients, in-frame mutations result in a truncated but partially functional dystrophin protein expressed at lower levels than in healthy muscle." (PMID 38671506, 2024). "In relation to women with Becker muscular dystrophy, DMD carriers had a higher proportion of left ventricular involvement, and among those who developed dilated cardiomyopathy during the 9-year follow-up, 91% were DMD carriers, with a median age of 53 years." (PMID 39075955, 2024). "This grouping was justified based on previous literature showing that Becker muscular dystrophy, a milder and slower-progressing form of muscular dystrophy compared to DMD, is associated with > 10% of muscle fibers expressing a truncated form of dystrophin." (PMID 38229112, 2024). "Also, a screening of 62 Becker muscular dystrophy patients revealed that 35 of them had dystrophin abnormalities." (PMID 37759719, 2023).